STAT3 (signal transducer and activator of transcription 3)
Diseases named in the same sentence as STAT3 in open-access papers (continued):
Sharing a sentence is not in itself a finding about the gene and the disease.
cancer (continued). "IL-8 has been well-characterized in tumorigenesis and has been shown to induce not only proliferation but also blood vessel angiogenesis, invasion, chemotaxis, and apoptosis regulation through STAT3/NF-κB in several cancer types." (PMID 34063134, 2021). "A mechanism whereby PDS5B depletion promotes proliferation of cancer cells is possible through the IL-6/STAT3/cyclin D axis." (PMID 34070827, 2021). "In particular, IL-1β extends the survival of endothelial cells by stimulating the production of VEGF by vascular smooth muscle cells and contributes to cancer invasiveness by activating STAT3." (PMID 34944856, 2021). "STAT3 target genes, VEGF, IL-10, and IL-6 are transcriptionally regulated by STAT3 and are propagated from cancer cells to immune cells." (PMID 34639131, 2021). "This confirms that STAT3 is one of the most commonly activated transcription factors in human cancer." (PMID 33802972, 2021). "In other reports, STAT3 signaling was found to be highly involved in the resistance of various cancer types." (PMID 33920736, 2021). "Signal transducer and activator of transcription 3 (STAT3) plays a pivotal role in the tumorigenesis and metastasis of numerous cancers, and STAT3 signaling is aberrantly activated in TNBC cells." (PMID 33920736, 2021). "Recent evidence shows that the 1,3,4-oxadiazole scaffold is frequently used in the structure of STAT3 inhibitors active against various cancer cells." (PMID 34066442, 2021). "This will block the formation of other oxygenating products based on STAT3:CT providing another way of eradicating cancer cells." (PMID 33544704, 2021). "STAT3 has been shown to be a major mediator of resistance to RT and chemoradiotherapy in almost all common types of cancer." (PMID 34830176, 2021). "Prior studies have shown the anti-cancer effects of ATQ by inhibiting STAT3 and mitochondrial respiration." (PMID 34071408, 2021). "The signal transducer and activator of transcription 3 (STAT3) is another tumor-promoting factor related to cancer progression." (PMID 34769099, 2021). "Generally, STAT3 and NF-κB activation enhances the aggressiveness and metastatic potential of cancer cells via the induction of EMT by the upregulation of EMT-inducing transcription factors, including slug." (PMID 34440829, 2021). "Among them, transcription factors (TFs) such as NF-κB and Signal Transducer and Activator of Transcription 3 (STAT3) are crucial in mediating inflammation and cancer development." (PMID 34503246, 2021). "Activation of STAT3 has been found in various cancer types and inhibition of STAT3 leads to decreased proliferation in cancer." (PMID 33804856, 2021). "Dysregulation of STAT3 activity is related to the pathogenesis of a variety of cancers, including breast, colon, cervical, and prostate cancer." (PMID 34059647, 2021). "The present study provided evidence that PI3K/Akt/NF-κB/mTOR/STAT3/CDK6 signaling network collectively contributes to generating cancer stemness in GBM." (PMID 34572040, 2021). "Molecular mechanisms dictating the cancer cell-intrinsic responsiveness to nintedanib such as STAT3 activation and lysosomal trapping were both amenable to pharmacological intervention with silibinin." (PMID 34439322, 2021). "JAK/STAT3 signaling, which regulates many aspects of cancer development and progression, promotes invasion and metastasis through activation of key metastasis promoting genes." (PMID 34365903, 2021). "It is generally known that the signal transducer and activator of transcription 3 (STAT3) pathway participate in a series of biological processes in human cancers, including cell proliferation, survival and apoptosis." (PMID 34345204, 2021). "Constant activation of STAT3 and/or JAK2 are associated with cell proliferation in several cancers including breast, pancreatic, and lung." (PMID 33596259, 2021).
cancer (continued). "Signal transducer and activator of transcriptions (STATs), specially STAT3 and STAT5 are implicated in cancer cell survival, proliferation, migration and apoptosis inhibition." (PMID 33544704, 2021). "STAT3 activated by phosphorylation on a tyrosine residue (Tyr 705) has been shown to be essential for muscle wasting in cachexia in cancer." (PMID 34003837, 2021). "Signal transducer and activator of transcription 3 (STAT3) is activated by phosphorylation on receptor-associated Janus kinases (JAKs), and regulates the proliferation and self-renewal ability of cancer stem cells through repression of KDM6B expression." (PMID 34950587, 2021). "Considerable evidence corroborates the presence of active STAT3 in greater than 95% of cancers, leading to diminished apoptosis." (PMID 34488773, 2021). "The use of various cancer-induced cachexia in vitro models allowed the demonstration of a key involvement of IL-6/STAT3 signaling in the process of skeletal-muscle wasting." (PMID 33557173, 2021). "It has been proved that the IL6/JAK/STAT3/SIGNALING pathway was aberrantly hyperactivated in various types of cancer that had a strong relationship with poor clinical prognosis." (PMID 34712264, 2021). "Results of GSEA analysis also revealed the associations of GGH with other cancer-related molecular pathways, including DNA replication, cell cycle, MAPK, KRAS, STAT3, and B cell receptor." (PMID 35082830, 2021). "It seems to be supported by others, as a restoration of PTPRK expression in cancer cell lines resulted in a reduction of phosphorylated extracellular signal-regulated kinases 1 and 2 (Erk 1/2), protein kinase B, (Akt), STAT3, and STAT5." (PMID 33921897, 2021). "STAT3 activation is attributed to both the progression and chemotherapeutic resistance of cancers, including OS." (PMID 33382511, 2021). "For example, the expression levels of IL-6 and the JAK/STAT3 pathway are elevated in degenerative lumber disc tissues, which have often been observed in various cancer tissues." (PMID 34321087, 2021). "The IL-6/JAK/STAT3 pathway plays a key role in the growth and development of many human cancers, and elevated IL-6 levels stimulate the overactivation of JAK/STAT3 signaling, which is usually related to poor patient outcomes." (PMID 34926575, 2021). "The exploration of STAT3 as a critical pathway in resistance of targeted therapy of oncogene-driven cancers would advance the broader application of STAT3 inhibitors." (PMID 33391507, 2021). "In cancer, IL-6 and STAT3 are related to the induction of senescence and in lung fibroblasts, STAT3 is an important factor driving oxidant-induced senescence." (PMID 34207510, 2021). "In the liver, STAT3 is activated in cholangiocytes enhancing cholangiocytic cancer stem cell for proliferation downstream to the signalling of CD24 and NANOG." (PMID 34047814, 2021). "TGF-β induces the release of IL-6 via the NF-κB signaling pathway, whereas IL-6 promotes cancer stemness through STAT3 activation." (PMID 34202411, 2021). "Abnormal STAT3 signals promote the occurrence and development of a variety of human cancers by inhibiting apoptosis or inducing cell proliferation, angiogenesis, invasion, and metastasis." (PMID 34079469, 2021). "Regarding the cross-talk between NF-kB and STAT3 signaling, it has been shown in a variety of cancers." (PMID 34885115, 2021). "Most of them demonstrated the ability to inhibit cell growth of several cancer lines for the suppression of the binding of STAT3 to its pY-peptide ligands and thus blocking IL-6–STAT3 activation, nuclear translocation, and transcriptional gene activation." (PMID 35047557, 2021). "Other experiments showed the accumulation of reactive oxygen species, suppression of NF-ƙB, STAT-3 inhibition participate in the suppression of cancer cells in the presence of TQ." (PMID 33663486, 2021). "Activated JAK/STAT3 signaling has been validated as a promising molecular target for cancer therapeutics discovery and development." (PMID 34365903, 2021).
cancer (continued). "On the other hand, the resistance mechanism study of compounds 8, 12, and 26 showed that the derivatives can inhibit the ability of phosphorylation of STAT3 to poison resistant cancer cells." (PMID 34577615, 2021). "It remains to be determined if STAT3 activation is a shared feature in activated CAFs across all cancers." (PMID 34858425, 2021). "Since S1PR1 is crucial for STAT3 activation in cancer cells, they found that overexpression of miR-133b markedly reduced the expression levels of STAT3 in the phosphorylated form." (PMID 35201458, 2021). "This provides fundamental insights into the mechanisms of pathogenesis of a lethal virus, and biology of STAT3, a critical player in immunity, development, growth and cancer." (PMID 34166464, 2021). "Overexpression of the SOCS proteins can inhibit the activity of STAT3 and thus promote apoptosis of cancer cells." (PMID 34976809, 2021). "Ectopic overexpression and constitutive activation of STAT3 can prevent the tumoricidal effects of nintedanib on cancer cells." (PMID 34439322, 2021). "The STAT3 pathway is a classic signaling pathway in cells that is also closely related to the progression of cancer." (PMID 35008530, 2021). "Leelamine from pine bark shuts off phosphoinositide 3-kinase (PI3K), mitogen-activated protein kinase (MAPK), and signal transducer and activator of transcription 3 (STAT3) pathways in cancer cells." (PMID 34205739, 2021). "Specifically, Bcl-xL is induced by oncogenic STAT3 signaling and displays elevated expression in various types of cancer, including head and neck SCC." (PMID 34066207, 2021). "In cancer, STAT3 activates genes of anti-autophagy proteins like BCL2, BCL2L1, and MCL1, which disrupt the formation of the complex BECN1/PIK3C3, essential for autophagy." (PMID 34207510, 2021). "As an anti-cancer agent, embelin suppressed the signal transducer and activator of transcription 3 (STAT-3) pathway to suppress cell proliferation and invasion in cancer cells." (PMID 33669814, 2021). "Another pathway involved in cancer cell death is signal transducer and activator of transcription 3 (STAT3) signaling." (PMID 35284036, 2021). "Since the overexpression or persistent activation of STAT3 plays a critical role in the malignant progression in cancer cells, we then examined the effects of ouabain on STAT3 in the A549, Hela, HCT116 and PANC1 cells." (PMID 34277430, 2021). "On the other hand, it is also conceivable that, prior to treatment, a subpopulation of cancer cells is primed to quickly engage the STAT3 feedback system during drug treatment." (PMID 34071428, 2021). "Nifuroxazide acts as an effective inhibitor of the STAT3 signaling pathway by reducing Jak2 autophosphorylation in cancer cells." (PMID 34833950, 2021). "Ethanolic extract of CP, CP-isolated xanthone and quercetin have been reported to attenuate the expression of NF-κB and STAT3 in several cancer cell lines." (PMID 34299510, 2021). "STAT3 is an oncogene that promotes cell survival, proliferation, and the progression of cancer cells." (PMID 34564613, 2021). "As reviewed in detail elsewhere, various in vivo and in vitro data demonstrated hyperactivation of JAK/STAT signaling, especially STAT3, in cancer cells contributing to cancer progression and radio- and chemoresistance." (PMID 33916057, 2021). "The transcription factor STAT3 is considered as a survival or progression factor in different cancer types affecting the response of certain tumors to chemotherapy." (PMID 34469022, 2021).
cancer (continued). "Emerging evidence reveals that the STAT3 and PD-L1 are critically involved in cancer proliferation, cancer progression and immunosuppression." (PMID 34440920, 2021). "In fact, S1PR1 has been found to persistently activate signal transducer and activator of transcription 3 (STAT3), of which STAT3 has been known to trigger various pathways that promote acquisition of cancer hallmarks." (PMID 34820423, 2021). "In different types of human cancers, Jak2/STAT3 signaling is continuously triggered and stimulates tumorigenesis and metastasis by facilitating the expression of cell cycle regulators and angiogenic factors." (PMID 34833950, 2021). "Meanwhile, cancer patients with EGFR-TKIs acquired resistance have a high level of phosphorylated STAT3 in some degree 19, 21-24." (PMID 33391507, 2021). "MMP9 is secreted by paracrine cancer cells with high STAT3 signal transduction, and STAT3 can regulate MMP9." (PMID 34876128, 2021). "The STAT3 signaling pathway has shown a pivotal role in cancer cell migration, invasion, metastasis and drug resistance of TNBC cells." (PMID 34445170, 2021). "Other cytokines, specifically IL-6 and OSM, clearly have more profound effects in cancer through STAT3—this has left LIF in the proverbial wayside, as more potent activators of STAT3 have been targeted for study." (PMID 34395259, 2021). "On the other hand, genetic instability of SNP allele rs351855-A in fibroblast growth factor receptor 4 (FGFR4) enhances STAT3 cascade and shapes TME in multiple cancer types, attributed to STAT3-pY705 elevation." (PMID 33957948, 2021). "Our in vitro findings presented here suggest that CDCP1-mediated activation of the Src-STAT3 pathway contributes to malignant progression by inducing invasion-like and growth-promoting phenotypes, even in cancer cells." (PMID 33574034, 2021). "Most interestingly, recent data report that STAT3 target genes are overexpressed in tumour-initiating cancer stem cells." (PMID 34473253, 2021). "Increased EZH2 in cancer cells after chemotherapy activated the transcription factor STAT3 and bound to the promoter regions of miR-378a-3p and miR-378d." (PMID 33823894, 2021). "In these two cancer cell models, the pro-apoptotic stimuli triggered by SZ-685C were the modulation of the Stat3 (signal transducer and activator of transcription 3)/Jabl/p27 signaling pathway and the downregulation of miRNA-205." (PMID 34068184, 2021). "STAT3 is thought to be highly involved in cancer invasion, migration, metastasis, and angiogenesis, and plays an important role in cancer immune escape." (PMID 34679602, 2021). "The EBV lytic protein BRLF1 activates the IL6/JAK/STAT3 pathway and promotes cancer by inducing cell migration in NPC cells." (PMID 35008199, 2021). "The functions of STAT3 in vivo have been extensively studied in both health and disease, particularly in cancer." (PMID 33557010, 2021). "Recently, studies in EGFR-positive cancer cells have shown that sustained activation of STAT3, due to enhancement of its binding to FGFR1, plays a key role in the acquisition of resistance to EGFR inhibitors." (PMID 34830951, 2021). "STAT3 is constitutively activated in many cancers, promoting cancer progression, proliferation, metastasis and drug resistance via the regulation of signalling pathways including Akt." (PMID 34680055, 2021). "STAT3 is an oncogene constitutively activated in both A549 and MDA-MB-231 cells used in this study and has been reported to be associated with cancer cell viability/proliferation, migration, and invasion." (PMID 35008855, 2021). "NF-κB or STAT3 promoter activation was increased gene expression of MMPs that signals induce cancer metastasis." (PMID 34638797, 2021).
cancer (continued). "Both pathways can activate transcription factors, such as NF-κB (nuclear factor-κB), HIF1α (hypoxia-inducible factor 1α) and STAT3 (signal transducer and activator of transcription 3), in cancer cells." (PMID 33513730, 2021). "The oncogenic functions of STAT3 have been extensively related to cancer cell proliferation, anti-apoptosis, migration, invasion, angiogenesis, stemness properties and immune suppression." (PMID 33391405, 2021). "These include transcription factors like STAT3 and members of the NF-κB protein family, that seem to be crucial in linking chronic inflammation to cancer development." (PMID 33673719, 2021). "Consistent with this, knocking down STAT3 in the BEZ235-treated cancer cells significantly augmented the pro-apoptotic effect of BEZ235." (PMID 33431808, 2021). "The disease‐specific role of STAT3 activated signalling in the immune response, inflammatory disease and cancer warrants further investigation." (PMID 33382511, 2021). "As a driver of immune evasion in cancer it is conceivable that inhibition of STAT3 enhances anti-tumor immune responses." (PMID 34440253, 2021). "Considering the results of these studies together, it is remarkable the relevant role of cytokines, in particular of IL-6, in the activation of STAT3 signaling pathway, which finally allows cancer cells to become more resistant to IR." (PMID 34141616, 2021). "An early study demonstrated that the S1P-S1PR1 pathway reciprocally regulates STAT3 activity, which is crucial for malignant progression in cancer cells." (PMID 34059068, 2021). "During hypoxia, STAT3 is activated in cancer cells by ROS, mTORC1, and/or IL-6, and further induces HIF-1a." (PMID 34440220, 2021). "The cytotoxic effect of ATZ-502 was demonstrated in several cancer cells by blocking the nuclear translocation of pSTAT3, STAT3, EGFR, and ErbB2 by karyopherin β1." (PMID 33801927, 2021). "The STAT3 is intensively studied because of its involvement in inflammation, cancer, and neurodegeneration." (PMID 34685476, 2021). "Many oncogenic proteins involve in the cancer progression including signal transducer and activator of transcription 3 (STAT3), an oncogenic transcription factor, which participates in the cell apoptosis, proliferation and autophagy." (PMID 33981228, 2021). "Recent studies have shown that niclosamide can treat cancer by controlling several signaling pathways such as the Wnt, STAT3, and Notch pathways." (PMID 34298652, 2021). "Previous reports have demonstrated that cancer cells harboring aberrant STAT3 activities elevate levels of anti-apoptotic proteins such as BCL2, BCL-xL, and myeloid cell leukemia 1 (MCL1)." (PMID 34268250, 2021). "It has been further elucidated that constitutively activated STAT3 maintains constitutive NF‐kB activity in cancers by inhibiting its export from the nucleus." (PMID 33634982, 2021). "Although many studies propose Tris DBA as a modulator of MAPK, Akt, phospho-S6 kinase, and N-myristoyltransferase-1, we have comprehensively demonstrated for the first time that Tris DBA is an inhibitor of STAT3 signaling in preclinical cancer models." (PMID 34771643, 2021). "Seven different STATs (1, 2, 3, 4, 5a, 5b, and 6) have been found in mammalian cells until now, and of all the STATs, STAT3 is certainly the most eminent among cancers." (PMID 34257541, 2021). "Activation of IL-6/STAT3 signaling induces HCC cancer stemness and promotes HCC cancer stem cell expansion." (PMID 33669204, 2021). "Several cellular pathways have been proven to take part in cancer-related inflammation, among which the most prominent is the NF-κB pathway and interleukin 6 (IL-6)/STAT3 signaling." (PMID 33990540, 2021). "Bi-stable regulation of the STAT1 and STAT3 can induce a phenotypic onset that promotes or suppresses cancer progression." (PMID 34631119, 2021).